CD4 (CD4 molecule)
Diseases named in the same sentence as CD4 in open-access papers (continued):
Sharing a sentence is not in itself a finding about the gene and the disease.
anemia (continued). "Repeated measures linear regression models estimated the anemia-type associated change in the CD4 cell-count, QOL, body mass index (BMI) and frailty over 18 months." (PMID 30935133, 2019). "In multivariable analysis; ART regimen, CD4 count, dietary diversity, educational status, and sex were found to be significantly associated with anemia at a P-value of < 0 .05." (PMID 30909968, 2019). "A significant association was noted between anemia and CD4 T-cell count less than 200 cells/mm3 (P = 0.001)." (PMID 30759131, 2019). "The meta analysis results also indicated that CD4 count of HIV infected individual was found to have statistically significant association with anemia." (PMID 30459953, 2018). "In the multivariate analysis, co-infections and starting ART during pregnancy were risk factors for maternal anemia, while CD4 count higher than 200 cells/mm3 was protective." (PMID 30261855, 2018). "There were significant associations between anemia with CD4 cell count and WHO clinical stage before ART initiation." (PMID 29568529, 2018). "As would be expected, female patients, those with CD4 cell count less than 200cells/ul were at higher risk of anemia while those who were overweight had lower risk of anemia." (PMID 29334932, 2018). "Human immunodeficiency virus infection is frequently associated with anemia where patients with more advanced HIV disease or a lower CD4 cell count had higher rates of anemia." (PMID 30126450, 2018). "In summary, we have shown that IFNγ-producing CD4+ T cells contribute to anemia in a model of VL, via a mechanism that involves loss of both macrophages and mesenchymal stromal elements from the BM erythropoietic niche leading to dyserythropoiesis." (PMID 30619317, 2018). "WHO clinical stages and CD4+ T cell counts were found to be associated with the prevalence of anemia before ART initiation." (PMID 29568529, 2018). "In contrast to these results obtained using adoptively transferred wild type CD4+ T cells, CD4+ T cells isolated from IFNγ-deficient B6.Ifnγ−/− mice we unable to induce anemia, despite equally efficient engraftment and activation." (PMID 30619317, 2018). "In general anemia occurs at the beginning of treatment, in the first 12 weeks of use, and it is frequently associated with low CD4 count and advanced disease, as demonstrated in our data." (PMID 30261855, 2018). "Being female and a CD4 count <200 cell/ul were risk factors for anemia while BMI ≥30 kg/m2 and being on ART for more than 10 years were associated with reduced risk of anemia." (PMID 29334932, 2018). "Early mortality is associated with several factors including low baseline CD4 count, anemia, low BMI, and advanced WHO clinical stage which are known to be strong predictors of mortality." (PMID 29415015, 2018). "WHO clinical stages and CD4 + T cell counts were associated with the prevalence of anemia before ART initiation." (PMID 29568529, 2018). "In both populations, a number of variables were associated with greater severity of anaemia, including lower CD4 cell counts and higher HIV viral loads." (PMID 26792471, 2016). "In a multivariate Cox proportional hazards model, being male, in WHO Stage 3, having a CD4 count less than 50 cell/μL, having a BMI<25 kg/m2, and having moderate or severe anaemia, were factors independently associated with a higher risk of attrition." (PMID 27562473, 2016). "The result of the bivariate analysis showed that, there were significant association between undernutrition and presence of anemia and a CD4 counts of less than 200 cells/mm3." (PMID 27468351, 2016). "In multivariate analysis, young age (<5 years; P = 0.014), fever (P = 0.012) and CD4 T cell count (200–499; P = 0.00017) were independent risk factors significantly associated with anaemia." (PMID 27682438, 2016). "In contrast, lower CD4 cell counts and moderate and severe anaemia were independently associated with a higher risk of TB, while a history of previous treatment for TB was protective." (PMID 26275908, 2015).
anemia (continued). "Anemia was associated with stunting and poor disease control (detectable viral load and low CD4 counts)." (PMID 26482352, 2015). "In this study, low CD4 cell count was associated with anemia at baseline although the reasons for such association are not clear." (PMID 26045966, 2015). "The risk of developing anemia in patients with low CD4 count was 3.8 times more than those with higher CD4 count of >350 cells/μL (P = 0.03, 95% CI: 1.6–9.4)." (PMID 25878898, 2015). "Independent risk factors for anemia were stunting, CD4 < 25 %, detectable viral load ≥400 copies/ml and vitamin A deficiency." (PMID 26482352, 2015). "At baseline, low BMI was associated with low hemoglobin levels and CD4 counts, while anemia was associated with low CD4 counts and female sex." (PMID 26825478, 2015). "Risk of death was higher in those with anemia (HR = 2.8), during periods of low CD4 count (HR = 5.1), for those with an abnormal chest X-ray (HR = 1.9) and those receiving empirical treatment for TB (HR = 3.7)." (PMID 24679187, 2014). "In a previous study, CD4 + T-cell count < 200 cells/μL was associated with an increased risk of anaemia." (PMID 24479873, 2014). "In a univariate analysis, CD4 count and gravidity were significant risk factors for anaemia in pregnancy, RR 1.41; 1.23–1.61 (p<0.001) and 1.10; 1.01–1.18 (p = 0.02) respectively." (PMID 25222119, 2014). "This study also confirms the findings of other studies that have shown an association between low CD4 counts and the presence or development of anemia, neutropenia and thrombocytopenia." (PMID 25209550, 2014). "After adjusting for antiretroviral regimen, age and gravidity in a multivariable analysis, only CD4 count remains a significant risk factor for anaemia in pregnancy and post-delivery." (PMID 25222119, 2014). "First of all, our study included a high number of patients with advanced immunological deterioration (41.8% of patients had a CD4 cell count <200 cells/μL), which has been associated to the development of anemia during HIV infection." (PMID 25005803, 2014). "After adjusting for antiretroviral regimen, age and gravidity in a multivariable analysis, only the CD4 count remains a significant risk factor for anaemia in pregnancy and postdelivery." (PMID 25222119, 2014). "Data were also lacking on the use of nonantiretroviral medications such as co-trimoxazole, which are more commonly prescribed among those with a low CD4 count and can be associated with adverse effects such as anaemia." (PMID 24245861, 2014). "After adjusting for year of ART initiation, sex, age, baseline CD4 count, baseline anaemia and NRTI, a strong association remained and NVP patients were almost 60% more likely to fail than EFV patients (aRR: 1.58; 95% CI: 1.13–2.22)." (PMID 25361827, 2014). "There was a significant association between anemia with CD4 cell count and TB before HAART initiation." (PMID 25335859, 2014). "Empirical treatment was more frequent with a lower CD4 count, anemia, weight loss and those who reported past opportunistic disease." (PMID 24679187, 2014). "In a multivariable analysis, after adjusting for the antiretroviral regimen (ZDV or D4T/3TC/NVP), the lower CD4 count (<200 cells/mm3) remained a significant risk factor for anaemia during pregnancy and post-delivery." (PMID 25222119, 2014). "That study also showed that CD4 count<200 cells/mm3 was associated with an increased risk of anemia." (PMID 24058490, 2013). "In established HIV infection, lower haemoglobin levels have been shown to correlate with decreasing CD4+ cell counts and many studies have found an association between anaemia during established infection and a faster progression to AIDS and death." (PMID 24238076, 2013). "Females, lower BMI, WHO stage III/IV, lower CD4 count, and zidovudine use were associated with increased risk of developing anemia during follow-up." (PMID 24069036, 2013).
anemia (continued). "The logistic regression analysis showed that older age, lower CD4 count and minority ethnicity were significantly associated with an increased risk of anemia." (PMID 24058490, 2013). "Older age, lower CD4 count and minority ethnicity were significantly associated with an increased risk of anemia." (PMID 24058490, 2013). "For instance, a study carried out among Rwandan women shows risk factors for anemia to be associated with lower body mass index (OR 3.4; 95% CI 2.4–4.1), and CD4 lymphocyte counts below 200 cells/μL (OR 2.41; 95% CI 2.01–3.07)." (PMID 23573191, 2013). "During FV infection CD4 T cells mediate immunopathology as evidenced by bone marrow pathology, anemia, and weight loss via local IFNγ production by FV-specific CD4 T cells." (PMID 23717308, 2013). "Virologic failure with immunologic success (VL-/CD4+) was associated with anemia (OR 1.80; 95% CI: 1.13-2.88, p=0." (PMID 23452915, 2013). "In multivariable analysis baseline weight loss >10%, low CD4, severe anemia, being diagnosed with TB solely through laboratory investigations and not initiating ART, were independently associated with increased risk of death." (PMID 23185278, 2012). "Weight loss >10%, low CD4 count (<200 and especially <50) and severe anemia were also significant risk factors for death." (PMID 23185278, 2012). "Factors associated with anaemia were female sex, low baseline haemoglobin level, low baseline CD4 count, more advanced disease stage, and initial cART containing zidovudine." (PMID 22289654, 2012). "Anemia remained an independent factor associated with death, also after adjustment for CD4 count and ART (p = 0.008)." (PMID 21827653, 2011). "In particular, it will be important to identify how the mutation leads to profound anemia and B-lymphopenia whilst neutrophils and T-cell numbers (including CD4/CD8 ratio) and function (responses to mitogens PHA and Con A) appear normal." (PMID 21750681, 2011). "In HIV naïve patients, a CD4+ Cell Count <200 cells/mm3 was associated with an increased risk of anemia." (PMID 20727136, 2010). "Only CD4+ Cells Count <200 cells/mm3 was associated with an increased risk of anemia in the multivariate analysis OR 16.95 (IC95% 1.7-29.6; p = 0.07)." (PMID 20727136, 2010). "Only CD4+ Cells Count <200 cells/mm3 was associated with increased risk of anemia in the multivariate analysis." (PMID 20727136, 2010). "In established HIV infection, lower haemoglobin levels have been shown to correlate with decreasing CD4+ cell counts and multiple studies have found an association between anaemia during established infection and a faster progression to AIDS and death." (PMID 18286183, 2008). "We showed that exuberant virus-specific CD4+ T cell response to FV infection resulted in bone marrow immune pathology and anemia, the severity of which crucially depended on the balance between FV-specific pathogenic CD4+ T cells and Treg cells." (PMID 19006695, 2008). "This woman presented at pre-entry biological parameters known to be associated with anaemia, such as low CD4 count (80 cells/mm3) and high HIV RNA viral load (5.33 log copies/ml)." (PMID 17476315, 2007). "Similarly, a low CD4/CD8 ratio was inversely associated with normal CD4 + count (aOR = 0.06, 95% CI: 0.02–0.20; p < 0.001), and anaemia was also inversely associated with normal CD4 + count (aOR = 0.32, 95% CI: 0.15–0.69; p = 0.003)." (PMID 40684209, 2025). "Higher CD4 cell count at enrollment was significantly associated with a lower odds of mortality in unadjusted models (OR, 0.69 [95% CI.55–.87), and grade ≥3 anemia with a significantly greater odds of mortality (4.86 [1.71–13.81])." (PMID 39906320, 2025). "Also, the frequent administration of recombinant erythropoietin (rhuEPO) for the correction of end-stage renal disease-induced anemia is considered to be one of the causes of LT apoptosis, especially CD4+ LTs." (PMID 38921685, 2024).
anemia (continued). "The BD FACSPresto method is particularly valuable in this context as it facilitates the detection of anemia, which is an adverse effect associated with Zidovudine, a commonly used in resource-limited regions, and allows for CD4+ T lymphocyte monitoring within a single hospital visit." (PMID 39768973, 2024). "We sought to determine whether there is an association between severe anemia or thrombocytopenia (requiring replacement therapy) and CD4+T lymphocyte levels." (PMID 39330902, 2024). "We subsequently attempted to determine whether there was an association between low hemoglobin levels (indicative of anemia in patients requiring transfusion) and low CD4+T lymphocyte count in the patients from our case series." (PMID 39330902, 2024). "We aimed to investigate whether anemia and thrombocytopenia requiring replacement therapy are influenced by the CD4+T lymphocyte counts and to identify the associated risk factors." (PMID 39330902, 2024). "However, nutritional causes, such as iron deficiency, are likely in our study population as evidenced by the association of anaemia with low BMI and low CD4:CD8 ratio." (PMID 35022106, 2022). "Similarly, studies conducted in Northwest Ethiopia, Nepal, Uganda, and China showed that low CD4 cell count was significantly associated with anemia." (PMID 35333889, 2022). "Study from USA, Iran, Ghana and Uganda reported an association between lower CD4 count and anemia." (PMID 35245289, 2022). "In this study we show that anemia was associated with a more pronounced inflammatory profile in HIV-TB coinfected persons in a cohort of 159 individuals with advanced HIV disease (CD4 count < 100 cells/μL) recruited as part of a randomized clinical trial (NCT00988780)." (PMID 35812431, 2022). "Within this population, clinical assessments and simple tests were strong risk factors for adverse outcomes, with independent associations between each of anemia, lower CD4 count, lower BMI, detectable urine LAM, presence of TB-related symptoms, and hospitalization/death." (PMID 35855000, 2022). "Additionally, we noted an association between anemia (Hb ≤ 12 g/dL) and higher concentrations of β2M with increased frequencies of CD4+CD69+ T cells (p = 0.08 and p = 0.02, respectively)." (PMID 34502204, 2021). "In this study of 15,126 PLWH in care in the current treatment era (2010 and after) in the US, we observed that factors including older age, female sex, black race, HCV coinfection, lower CD4 cell counts, VL ≥400 copies/ml and lower eGFR were associated with an increased risk of anemia." (PMID 32197585, 2020). "Studies conducted in India, Nigeria, and South Africa indicated that HIV-infected patients with age > 30 years, male gender, hemoglobin level < 11 g/dl, body weight < 45 kg, coinfection with HIV and TB, and CD4 count < 100/μl at baseline had significantly higher risk for anemia." (PMID 32258143, 2020). "Lower CD4 cell count has been previously identified as a risk factor for anemia." (PMID 32197585, 2020). "In these cases, anaemia was associated with minority ethnicity, older age and lower CD4 counts." (PMID 30816082, 2019). "Having low CD4 count became significantly associated with anemia in this study." (PMID 31596865, 2019). "This may be an important biological implication to our finding in that the mean hemoglobin level increased with increasing CD4 count, and lower CD4 count was associated with an increased risk of anemia." (PMID 30909968, 2019). "Lower CD4 counts were found to be an independent risk factor of anaemia in our study." (PMID 30816082, 2019). "The independent risk factors of anaemia were lower CD4 counts, co-infected with PM or TB." (PMID 30816082, 2019). "In addition, anemia and low serum total cholesterol were found to be independently associated with CD4 T cell count < 200 and/or stages III/IV (p < 0.05)." (PMID 30064395, 2018).
anemia (continued). "Using gene-deficient mice or neutralizing antibodies it was shown that the sequential production of IFN-γ by NK, NKT, as well as CD8+ and CD4+ T cells during the early stage of trypanosome infection seems to be crucial to initiate acute inflammation-associated anemia, also termed consumptive anemia." (PMID 29497418, 2018). "Among patients with similar CD4 cell counts, heightened inflammation may drive higher mortality in a subgroup, who might be identified through weight loss, anemia, and hypoalbuminemia." (PMID 29514235, 2018). "Il2 deletion in the CD4+ T-cell compartment resulted in characteristic IL-2 Deficiency Syndrome24–26 originally described in Il2KO mice and characterized by severe anemia, splenomegaly, uncontrolled expansion of splenic T cells associated with reduction of Treg cells and loss of B cells." (PMID 29549257, 2018). "Similarly, our multivariate analysis showed that low CD4 count is a risk factor associated with anemia." (PMID 30261855, 2018). "There was significant association between dyslipidemia and CD4 cells count, as well as anemia." (PMID 29610642, 2017). "It has also been shown that the likelihood of developing anemia increases with immunological deterioration and the risk of having anemia in patients with CD4<200cells/μl is more than 9 times as compared to patients with CD4>500 cell/μl." (PMID 27200131, 2016). "Although our study did not indicate any significant association with intestinal parasitic infestation, the triple burdens of HIV, intestinal parasitic infections and anemia often coexist in children, and are often associated with lower CD4+ T cell levels in HIV infected children." (PMID 26482352, 2015). "Similarly, low BMI, low albumin and low CD4 counts were linked to anemia; while, hypoalbuminemia was associated with low hemoglobin levels and CD4 counts." (PMID 26825478, 2015). "The association of low CD4 cell count with anemia and leucopenia may be due to the dysregulatory effect of HIV on the function of early hematopoietic progenitor cells through the viral accessory protein Negative factor (Nef)." (PMID 25209550, 2014). "Older age, lower CD4 count and minority ethnicity are associated with an increased risk of anemia." (PMID 24058490, 2013). "Based on the strong association of virologic failure and VL-/CD4+ discordance and anemia obtained in our study, chronic infections with anemia may be interfering with immuno-virologic recovery on HAART." (PMID 23452915, 2013). "Similarly, the CD4% was significantly associated with the likelihood of anaemia, even after controlling for WHO clinical stage." (PMID 23114115, 2012). "This could be potentially beneficial for patients at risk of developing anaemia, e.g., female gender, patients with low CD4 counts and patients with advanced disease stage." (PMID 22289654, 2012). "In addition, the two types of donor CD4+ T cells caused comparable levels of anemia in these T and B cell -deficient hosts, which results from bone marrow pathology." (PMID 22589728, 2012). "Anemia was associated with a low CD4-cell count (p < 0.001), and TB treatment (p < 0.001)." (PMID 21827653, 2011). "However, a study from Tanzania found that among women with World Health Organization (WHO) clinical stage 1 or 2 disease, anaemia was associated with a more rapid decline in CD4 cell count and an increased mortality." (PMID 18286183, 2008). "Our data indicated that development of anemia in this model was caused by FV-specific CD4+ T cells but could be suppressed by any Treg cell population, regardless of FV reactivity." (PMID 19006695, 2008). "Clinical signs of VL include fever, malaise, enlargement of spleen and liver, anemia, leukopenia, weight loss, hypergammaglobulinemia and progressive suppression of the CD4+ T cell response, with decreased numbers of CD4+ total counts and Leishmania-specific CD4+ T cells." (PMID 40230841, 2025).